BRCA1 (BRCA1 DNA repair associated)
Diseases named in the same sentence as BRCA1 in open-access papers (continued):
Sharing a sentence is not in itself a finding about the gene and the disease.
cancer (continued). "In parallel, this allowed the unfettered recruitment of the MRN complex to DSBs and rescue of HR in BRCA1 mutant cancers, leading to PARPi resistance." (PMID 32722408, 2020). "Three benchmarks were performed during the period 2017–2018 pertaining to specific cancer types grouped in three activity domains: solid tumors (benchmark 2017/1), hematological malignancies (benchmark 2017/2), and BRCA1/2 (benchmark 2018/1)." (PMID 33138022, 2020). "This raises the concept that ER negativity is neither a sequel of younger ages nor the graded tumours at onset of diagnosis, but is an intrinsic character related to BRCA1 positive cancers." (PMID 32334465, 2020). "Secondary mutations across various cancer types were discovered to cause the reversion of DDR protein or gene function, such as BRCA1/2, PALB2, and RAD51C/D, resulting in the restoration of HR repair function and nullifying synthetic lethality." (PMID 32883316, 2020). "The panel incorporates genes underlying well-characterized cancer syndromes, such as BRCA1 and BRCA2 (BRCA1/2), along with more recently discovered genes associated with increased cancer risk." (PMID 32090079, 2020). "Alternative splicing of cancer-associated genes such as fibroblast growth factor and insulin receptors, signaling kinases such as SRC and RAS, or the BRCA1 tumor suppressor have been reported from hnRNPA1-deregulated cells." (PMID 32417965, 2020). "Interestingly, the RASSF1A A133S SNP variant has been identified in a range of cancers, and its association with mutations in BRCA1/2—two other DNA repair genes—might indicate the inhibition of DNA repair as pathogenetic basis for the cancer association of this variant." (PMID 31963420, 2020). "The remaining two studies grouping BRCA1 with BRCA2 compared the patients with cancer in the same institute." (PMID 32349445, 2020). "Among these TFs, GABPA was most frequently enriched in the common region at BRCA1 promoter in five cancer cell lines and liver tissues." (PMID 32000125, 2020). "BRCA1 loss or mutation leads to PARP inhibitor (PARPi) sensitivity, which has been exploited to treat BRCA1 mutant cancers." (PMID 32139898, 2020). "Consistent with the previous studies, both BRCA1 and BRCA2 genes contain several cancer risk regions." (PMID 32269964, 2020). "Nevertheless, it seems that the lethal interaction only happens in specific cell lineages, specifically the same ones where germline BRCA1 and BRCA2 mutations predispose to cancer." (PMID 32239503, 2020). "The cancer-associated BRCA1 variants R133H and E143K, and the RACK1 variant K280E, which decrease the binding of BRCA1 to RACK1, suppress the centrosomal localization of BRCA1." (PMID 32722046, 2020). "In conjunction, the Supreme Court of the United States overturned Myriad Genetics’ patent on the BRCA1 and BRCA2 genes, which allowed for the development of multi-gene cancer predisposition panels that today are offered by multiple commercial companies." (PMID 31963545, 2020). "Genetic testing for germline pathogenic variants in BRCA1 and BRCA2 is widely used in clinical practice to identify individuals at increased risk of breast, ovarian, and other cancers." (PMID 31853058, 2020). "This was independent from the type of germline mutation, BRCA1 or BRCA2 and was true for both types of cancers when analyzed independently." (PMID 32164626, 2020). "Thus, the CST cell line could become an important tool for the research of BRCA1-mutated cancers." (PMID 32053991, 2020).
cancer (continued). "In a cohort of 888 women carriers of BRCA1 or BRCA2 mutations who underwent screening with annual TVUS and CA-125, 5 of 10 cancers were diagnosed in women who had had normal screening results 3 to 10 months previously." (PMID 33408585, 2020). "The aberrant hypermethylation of BRCA1 promoter CpG islands induces the decreased expression of BRCA1 (Breast Cancer 1) protein." (PMID 32235500, 2020). "A subset of sporadic TNBCs have defects in DNA repair and gene expression profiles typical of BRCA1-related cancers and they can be treated with therapeutic strategies based on deficiencies in DNA repair." (PMID 32456160, 2020). "Although we observed a predominance (23.2%) of BRCA1/BRCA2 variants in patients with HGSOC, these alterations were not exclusively associated with this group, as they were also frequently found in carcinomas with other histologies (10%)." (PMID 32850417, 2020). "Germline BRCA1/2 mutations (gBRCAm) confer an increased risk of breast and HGSOC, and, to a lesser extent, of other type of cancers such as certain pancreatic, prostate, stomach and colon cancers." (PMID 30909618, 2019). "Similar to the results of other studies, we observed an association between germline mutations in BRCA1/BRCA2 and a family history of cancer." (PMID 31244284, 2019). "In this study, we report that the ubiquitin‐specific protease 9X (USP9X) is a bona fide deubiquitinase for BRCA1 in human cancer cells." (PMID 31512408, 2019). "Here, specific genes are mutated in particular types of cancer, and patients harboring germline mutations at tumor suppressor genes, such as APC and BRCA1/BRCA2, exclusively develop cancers in specific organs." (PMID 31488818, 2019). "Several gene mutations have previously been described to rescue survival of BRCA1-deficient cells, but for BRCA2-deficient cancer cells this remains less clear." (PMID 30626869, 2019). "Women carrying germline mutations in the BRCA1 and BRCA2 genes have a high lifetime risk of developing breast, ovarian, and other cancers." (PMID 30747491, 2019). "qPCR analyses revealed that the mesenchymal markers (i.e. SNAI1, SNAI2, ZEB1, ZEB2, CDH2, vimentin and fibronectin) expression was decreased in cancer EVs-exposed BRCA1-KO fibroblasts, while the expression of CDH1 was increased." (PMID 31200749, 2019). "The BRCA Exchange, part of the BRCA Challenge, is a data-sharing initiative by the Global Alliance for Genomics and Health (GA4GH) and aggregates BRCA1 and BRCA2 data on the impact of genetic variation on cancer risk." (PMID 31013702, 2019). "Mutations of the RNA processing factors result in the increase of spicing isoforms of DNA repair proteins including BARD1β, FANCEΔ4, and BRCA1-Δ11q in cancers." (PMID 32010626, 2019). "Combined blockade of ATR and PARP is an effective therapeutic strategy for GBM, even in non-Myc PARPi-resistant GSCs, thus providing a much-needed therapeutic breakthrough for this deadly disease and possibly other BRCA1/2-wild-type or HR proficient cancers." (PMID 31266951, 2019). "In contrast, FLT3, BRCA1, BRCA2 and PIK3R1 mutations were more frequently detected in patients carrying germline cancer-associated variants." (PMID 30850667, 2019). "Previous studies have shown that RAD52 is required for viability of BRCA1- and BRCA2-deficient cells, suggesting a targeted treatment opportunity via inhibition of RAD52 to specifically kill cancer cells with BRCA deficiency." (PMID 31569559, 2019). "Germline mutations of the genes BRCA1 and BRCA2, which encode proteins essential for the repair of double-strand DNA breaks through homologous recombination, lead to increased cancer predisposition." (PMID 30691488, 2019).
cancer (continued). "The most cost-effective BRCA1/2 tests, as well as family history-based screening and cancer-based genetic screening, are all delivered predominantly via genetic services led by geneticists, followed by the medical specialist and the primary care models." (PMID 31275354, 2019). "Among seven genotyped cancer-affected members of these two branches (left half), six were carriers of BRCA1 c.4096+3A>G, and two of these developed OC." (PMID 31683985, 2019). "The expression of 349 miRNAs was aberrant in BRCA1-KO fibroblasts following treatment with cancer EVs, of which 169 miRNAs were down expressed and 180 miRNAs were over-expressed in cancer EVs-exposed BRCA1-KO fibroblasts." (PMID 31200749, 2019). "Inhibition of poly-(ADP-ribose) polymerase (PARP), a key enzyme in base excision repair, efficiently kills cancer cells with defective HR and PARP inhibitors (including olaparib) are now used for treatment of BRCA1/2-deficient breast and ovary cancer." (PMID 31619012, 2019). "The loss of homologous recombination (HR) genes such as BRCA1 and BRCA2 is deleterious to the survival of normal cells, yet it is tolerated in cancer cells." (PMID 30626869, 2019). "How germ-line BRCA1 haploinsufficiency preferentially leads to tissue-specific cancer development remains a longstanding conundrum." (PMID 30995943, 2019). "This study reveals a novel molecular mechanism that RD‐N promotes CTSB‐dependent DNA damage by the suppression of BRCA1 in PCa cells, leading to the identification of a potential compound that target lysosomes for cancer treatment." (PMID 30565390, 2019). "Inactivation not only of 53BP1, but also of its downstream effectors was shown to increase DNA damage tolerance of cancer-prone BRCA1−/− cells, most likely potentiating error prone HR pathways and increasing genome instability." (PMID 31380392, 2019). "Although the DNA damaging agents have shown clinical efficacy in PALB2-, BRCA1- or BRCA2- cancers, tumor cells often develop resistance to these drugs, with tumor recurrence and progression." (PMID 31877165, 2019). "Mutations of the genes BRCA1 and BRCA2 lead to increased cancer predisposition and are present in approximately 14% of epithelial ovarian cancers, according to recent population-based studies." (PMID 30691488, 2019). "In cancer cells, functions of BRCA1 are most established in homologous recombination, which can only be seen in dividing cells." (PMID 31861888, 2019). "A high incidence of somatic mutations of BCLAF1, U2AF65, U2AF35, SRSF2, SF3A1, SF3B1, and PRPF40B at the BRCA1/BCLAF1 mRNA splicing complex was reported in various cancer types." (PMID 32010626, 2019). "Cancer cells with deleterious mutations in BRCA1 or BRCA2 have defective HRR and the unrepaired DNA after treatment with PARPi will eventually lead to cancer cell death, a phenomenon called synthetic lethality." (PMID 31404966, 2019). "Somatic BRCA1 methylation data were available for 7307 cancers, somatic copy number calls for 7227 cancers, and Signature 3 data for 4548 cancers." (PMID 31360904, 2019). "Knowledge levels were high across the cohorts, irrespective of genetic status, education level and time since testing, showing that men retained accurate information about inheritance of BRCA1/BRCA2 mutations and cancer risk." (PMID 29802810, 2019). "A striking 50% methylation of BRCA1 was identified in the benign sample cohort, which marks the significance of assessing the hypermethylation pattern to detect cancer at its early stages." (PMID 31653147, 2019). "In parallel to RNA-Seq mining, we performed mRNA array analyses to search for transcripts differentially expressed in BRCA1-KO fibroblasts prior and following exposure to cancer EVs." (PMID 31200749, 2019). "An increasing body of evidence indicated that platinum-based regimen can be used for BRCA1/2 mutation carriers with TNBC, for whom cancer chemotherapy with anthracycline cannot be performed." (PMID 30975222, 2019).
cancer (continued). "BRCA1/2 is involved in maintenance of genome stability, and inherited mutations in these genes increase lifetime risk of developing HBOC-related cancers." (PMID 31666926, 2019). "This variant was shown to abolish the interaction of BRCA1 with the partner protein BARD1, in a manner similar to the known cancer predisposing variant p.Cys61Gly." (PMID 30696104, 2019). "In human cancer cell-lines with defective function of BRCA1, PALB2 or BRCA2, RAD52′s depletion increases damage-associated chromosomal abnormalities, decreases clonal viability, and also reduces the HR activity." (PMID 31652722, 2019). "Given the various degrees of functional deficiency of BRCA1 mutations in supporting super-enhancer activity, the in vitro system established in our study could serve as a convenient way of further exploring phenotype-genotype correlation for cancer-predisposing BRCA1 mutations." (PMID 30995943, 2019). "Our findings add to the current knowledge of BRCA1, and the role of its exon 11 in cancer pathogenicity, and will be of use in clinical genetic counselling." (PMID 31683985, 2019). "Out of these transcripts, 3045 were downregulated and 3941 transcripts were upregulated in cancer EVs-exposed BRCA1-KO fibroblasts." (PMID 31200749, 2019). "For example, ATR inhibition has been shown to sensitize PARP inhibitor‐resistant BRCA1 mutant cancer cells to PARP inhibition through blocking protection of stalled replication forks." (PMID 31529615, 2019). "The results showed that BRCA1 (P = 0.007) and BRCA2 (P = 0.000129) were selected the genes susceptible to cancer (differentially expressed genes)." (PMID 31865918, 2019). "Cancer cells carrying HR DNA repair molecular alteration, like BRCA1/2 defects, are selective target of the PARP inhibition, resulting in a synthetic lethal phenotype." (PMID 31877762, 2019). "While BRCA1 is obviously an important cancer gene, the clinical significance of recurrent BRCA1 E597K variant is not yet known." (PMID 30709382, 2019). "Collectively, these data have clearly demonstrated that down-regulation of BRCA1 can enhance cancer cell stemness in multiple tumor types." (PMID 31273285, 2019). "While normal cells treated with PARPi are able to efficiently repair DSBs using BRCA1/2-mediated HR, cancer cells carrying defects in HR accumulate high levels of toxic lesions that leads to synthetic lethality and apoptosis." (PMID 31615159, 2019). "Our findings help to explain the association of this variant with a lower cancer risk in BRCA2 mutation carriers and highlight the importance of genetic changes in BER pathway genes as modifiers of cancer susceptibility for BRCA1 and BRCA2 mutation carriers." (PMID 30747491, 2019). "Moreover, the validation of MET as a potent driver in BRCA1-associated tumorigenesis underscores the potential of iterative analysis of CNAs in progressively complex mouse models as an approach for identifying putative cancer genes that promote tumorigenesis in specific genetic contexts." (PMID 30674894, 2019). "Identifying BRCA1/2 PV carriers is crucial to offer appropriate care and preventive programs for both cancer patients and their healthy relatives." (PMID 31600986, 2019). "As costs have come down and the benefits of knowing one’s PV status are clear, there have been calls for population-based screening for BRCA1 and BRCA2, as well as other high-risk cancer genes." (PMID 30832243, 2019). "The cancer cell lines and primary cells obtained from the ascites of two patients diagnosed with BRCA1/2 wild type HGSOC were treated for 1 week." (PMID 31857852, 2019). "For some women with a BRCA1 and BRCA2 mutation, another strategy to reduce the elevated cancer risk is chemoprevention (e.g. tamoxifen, aromatase inhibitors)." (PMID 31370837, 2019). "Following this observation, we performed an interaction network analysis to connect the dysregulated miRNA expression in cancer EVs-treated BRCA1-KO fibroblasts to the regulated transcripts." (PMID 31200749, 2019).
cancer (continued). "In our material, we observed relatively advanced age of cancer diagnosis among BRCA1 carriers after RRSO." (PMID 30918533, 2019). "Germline mutations in BRCA1 and BRCA2 (BRCA)genes confer high risk of developing cancer, especially breast and ovariantumors." (PMID 31067289, 2019). "BRCA1 and BRCA2 (collectively termed BRCA) are cancer predisposition genes (CPGs) that have been used in clinical practice for over 20 years." (PMID 31360904, 2019). "GSEA from RNA sequencing indicates TIGAR KD produces a gene signature that is similar to BRCA1 downregulated cancer cells." (PMID 31508509, 2019). "In this study, we have presented the results of a targeted search for 9–12 del BRCA1 in a group of 764 patients and relatives cared for at the first Hereditary Cancer Clinic in Mexico." (PMID 31545835, 2019). "It has been demonstrated that protein annexin A1, A2, A4 and A5 play an important role in the occurrence and development of these two cancer types, and BRCA1 and BRCA2 gene mutations are commonly observed in both cancer types." (PMID 31405076, 2019). "A previous study also showed that certain transcriptional factor can bind and repress the transcription of BRCA1 from its bidirectional promoter in cancer." (PMID 31245179, 2019). "BRCA1 BRCT domain mutant cancers have previously been characterized and demonstrated low or undetectable protein expression." (PMID 31827092, 2019). "If molecular analysis was restricted to BRCA1/2 only the hereditary etiology of cancer would have been identified in 10.5% (126/264) of the cases." (PMID 31159747, 2019). "In the course of our study, we compared the migratory potential of BRCA1-KO fibroblasts exposed to EVs isolated from the sera of healthy individuals and cancer patients." (PMID 31200749, 2019). "We have found that BRCA1, a multifunctional protein involved in DNA repair and epigenetic regulation, plays a critical role in the regulation of cancer stem cell (CSC)-like characteristics." (PMID 31273285, 2019). "Our data strongly suggest that BRCA1 does not only regulate cancer cell fate but also affect how cancer cells respond to tumor microenvironmental stresses and therapeutic drugs." (PMID 31273285, 2019). "A number of RAD52 inhibitor leads were reported and showed effects to selectively kill BRCA1- and BRCA2-deficient cancer cells." (PMID 31569559, 2019). "The study includes 1246 individuals assessed for BRCA1/2 genetic testing in Navarra, during 2000–2016, and a cohort of BC (n = 4384) and OC (n = 561) from the population-based Navarra Cancer Registry." (PMID 31771539, 2019). "Current evidence- and expert opinion-driven guidelines as well as statistical models to identify potential candidates for BRCA1/2 testing are mainly based on the number of individuals with relevant cancers in a kindred, age(s) of diagnosis, and ancestry." (PMID 31892343, 2019). "If they are methylated in a distinct fraction of the population (using BRCA1 as “standard”; > 4%), one should assess the OR for individuals harbouring constitutional methylation to develop the same type of cancer." (PMID 31225507, 2019). "BRCA1 mutant carcinomas are sensitive to PARP inhibitor (PARPi) therapy; however, resistance arises." (PMID 31827092, 2019). "The most commonly mutated cancer susceptibility genes were BRCA2 (n = 31), BRCA1 (n = 22), ATM (n = 19), and MUTYH (n = 19)." (PMID 29684080, 2018).